KMT5A (lysine methyltransferase 5A)
Description:
Protein-lysine N-methyltransferase that monomethylates both histones and non-histone proteins. Specifically monomethylates 'Lys-20' of histone H4 (H4K20me1). H4K20me1 is enriched during mitosis and represents a specific tag for epigenetic transcriptional repression. Mainly functions in euchromatin regions, thereby playing a central role in the silencing of euchromatic genes. Required for cell proliferation, probably by contributing to the maintenance of proper higher-order structure of DNA during mitosis. Involved in chromosome condensation and proper cytokinesis. Nucleosomes are preferred as substrate compared to free histones. Plays a negative role in TGF-beta response regulation and a positive role in cell migration.
Synonyms: PR-Set7; PR/SET07; SET07; SET8; SETD8
Tractability: Small molecule: a structure with a bound ligand is known; a high-quality ligand is known; it has a high-quality binding pocket. PROTAC: UniProt records ubiquitination sites on it; ubiquitination databases record sites on it; a small molecule that binds it is known.
Target class: Writer; Protein methyltransferase; SET domain; Epigenetic regulator
Gene: Protein-coding gene on chromosome 12 (123,384,132 to 123,409,353, forward strand). Ensembl gene ENSG00000183955.
Subcellular location: Nucleus; Chromosome
Subcellular location (Human Protein Atlas): Nucleoplasm; Cytosol
Pathways (Reactome):
Cell Cycle: Condensation of Prophase Chromosomes
Cell-Cell communication: Negative Regulation of CDH1 Gene Transcription
Chromatin organization: PKMTs methylate histone lysines
Gene Ontology:
Molecular function: histone H4K20 methyltransferase activity; histone H4K20 monomethyltransferase activity; histone methyltransferase activity; protein binding; protein-lysine N-methyltransferase activity; transcription corepressor activity; histone H4 methyltransferase activity; lysine N-methyltransferase activity
Biological process: negative regulation of DNA-templated transcription; negative regulation of double-strand break repair via homologous recombination; negative regulation of transcription by RNA polymerase II; peptidyl-lysine monomethylation; mitotic chromosome condensation; regulation of transcription by RNA polymerase II; chromatin remodeling
Cellular component: chromatin; chromosome; nucleoplasm; nucleus; polytene chromosome
Genetic constraint (gnomAD): Loss-of-function variants: 6 observed, 37.77 expected, observed/expected ratio (o/e) 0.16, 90% interval 0.086 to 0.31. The upper end of that interval is the gene's LOEUF score, 0.31, which puts it in group 1 of 6, group 1 being the genes least tolerant of losing a copy. Missense variants: 308 observed, 438.22 expected, observed/expected ratio (o/e) 0.7, 90% interval 0.64 to 0.77. Synonymous variants: 153 observed, 165.67 expected, observed/expected ratio (o/e) 0.92, 90% interval 0.81 to 1.06.
Homologues: Orthologues: macaque KMT5A (99% identical), pig KMT5A (94% identical), rat Kmt5a (92% identical), mouse Kmt5a (84% identical), rat AABR07010705.1 (82% identical), guinea pig KMT5A (79% identical), chimpanzee KMT5A (56% identical).